CD24 (CD24 molecule)
Diseases named in the same sentence as CD24 in open-access papers (continued):
Sharing a sentence is not in itself a finding about the gene and the disease.
hepatitis B (3 papers, 2021 to 2024). "Previous findings showed that among healthy adults vaccinated against hepatitis B, the proportions of CD24+CD27+Breg and CD24+CD38high Breg cells were significantly lower in the anti-HBs-positive group than in the anti-HBs-negative group." (PMID 38555445, 2024).
Insulin resistance (3 papers, 2018 to 2023). Increased resistance towards insulin, that is, diminished effectiveness of insulin in reducing blood glucose levels. "Conversely, high expression of CD24-positive cells may be associated with insulin resistance and impaired adipogenesis." (PMID 33467499, 2021). "Furthermore, in Hashimoto’s thyroiditis (HT), associated with insulin resistance, the level of CD19+ CD24hiCD38hi regulatory B-cells (Bregs) was reduced, suggesting a potential role for CD24 in insulin resistance in these patients." (PMID 33467499, 2021). "Additional studies will be required to identify whether there is a potential mechanism among CD24, glucose uptake, and insulin resistance." (PMID 29769552, 2018).
laryngeal carcinoma (3 papers, 2016 to 2023). Carcinoma that arises from the laryngeal epithelium. "In total, 82% of all evaluated HNSCC samples, 91% of oropharyngeal cancers, 82% of cancers of the oral cavity, and 74% of laryngeal cancers were positive for CD24." (PMID 31661833, 2019). "In this study, we have shown that CD24 positivity marks for a residual cisplatin resistant population in laryngeal carcinoma lines." (PMID 27276062, 2016). "In this regard, CD24 expression level appears to be a significant molecular phenotype of cisplatin-resistant residual cells in laryngeal carcinoma lines." (PMID 27276062, 2016). "The percentage of CD24+ cells shows a linear relationship with the IC-50 values on the three laryngeal carcinoma lines." (PMID 27276062, 2016). "Another interesting outcome of modulating CD24 expression levels in these three laryngeal carcinoma lines is it affects the sphere forming/self-renewing ability." (PMID 27276062, 2016). "We initially aimed to assess the levels of CD24 expression in the three chosen laryngeal carcinoma lines to see if there is any correlation between surface level CD24 expression and the corresponding cisplatin sensitivity of the lines." (PMID 27276062, 2016). "To investigate whether CD24 percentage correlates with cisplatin resistance in these three laryngeal carcinoma lines, we performed a flow cytometry analysis." (PMID 27276062, 2016). "We then probed whether modulation of the levels of CD24 affected cisplatin resistance in the three laryngeal carcinoma lines and the expression of various pro-survival genes involved in cisplatin resistance." (PMID 27276062, 2016). "The positive correlation between the expression levels of CD24 and those of various pro-survival genes critical in mustering cisplatin resistance casts light on the vast scale of effects that CD24 expression has in maintaining the viability of laryngeal carcinoma cells." (PMID 27276062, 2016).
leiomyoma (3 papers, 2022 to 2026). A well-circumscribed benign smooth muscle neoplasm characterized by the presence of spindle cells with cigar-shaped nuclei, interlacing fascicles, and a whorled pattern. "In contrast, leiomyoma cultures exhibited widespread CD24/CD73 expression, focal CD49b clusters, high Ki67 positivity, metabolic reprogramming toward complex carbohydrate degradation, SLC-mediated transport, and a low-PLIN2/high-ACLY signature." (PMID 42099382, 2026). "HMGA2 and CD24 showed broader expression patterns and higher signal intensity in leiomyoma than in myometrial cells." (PMID 35884847, 2022). "Furthermore, highly upregulated mRNA of cell surface marker CD24 was detected in our cases which correlates with previous findings of enriched CD24hi cells in leiomyoma." (PMID 37466765, 2024).
liver disease (3 papers, 2020 to 2023). "A subpopulation of LCN2-expressing CD24+ LPCs was activated and expanded in ductular reaction foci with liver disease progressed." (PMID 37784089, 2023). "The CD19+CD24+CD38− primarily memory B cells were generally less in the diabetic than the non-diabetic groups irrespective of the liver disease stage." (PMID 33230233, 2020).
lung diseases (3 papers, 2022 to 2025). "EXO CD24 can suppress the hyperinflammatory response in the lungs in several pulmonary diseases with a significant unmet need for treatment options." (PMID 38203250, 2023).
medulloblastoma (3 papers, 2019 to 2026). A malignant, invasive embryonal neoplasm arising from the cerebellum. "Moreover, high CD24 mRNA levels were associated with poor survival in the first years following diagnosis in Group 3 medulloblastoma patients." (PMID 36825029, 2023). "Among the 19 immune checkpoint-related genes evaluated by nCounter in the Brazilian series of medulloblastomas, we found increased mRNA counts of CD24, CD276, CD47, and PVR (CD155)." (PMID 36825029, 2023). "We further assessed the association of CD276, CD47, CD24, and PVR expression profiles by nCounter and patient survival analysis in the 80 medulloblastomas Brazilian cohort." (PMID 36825029, 2023). "Here we report for the first time that CD24 is universally up-regulated across all medulloblastoma subgroups compared to normal brain tissue." (PMID 30657775, 2019). "Injections of 4x105 CD24+ primary Ptch1lox/lox;GFAPcre medulloblastoma cells resulted in 6 tumours from 15 transplantations (95.17+/-19.51 days) while equivalent numbers of CD24- cells gave 0 tumours following 9 injections (p = 0.021)." (PMID 30657775, 2019). "In conjunction with CD15, proliferating CD24+/CD15+ granule cell precursors (GCPs) were identified as a TIC population in Ptch1 deleted medulloblastoma." (PMID 30657775, 2019). "The CD15+/CD24+ population was significantly increased in the medulloblastoma model (P7: 23.25+/-1.59%; P17: 45.38+/-3.12%, p = 0.022) while the CD15-/CD24- population was significantly decreased (P7:28.4+/-3.68%; P17:10.78+/-1.78%, p = 0.011)." (PMID 30657775, 2019). "Co-immunohistochemistry/in situ hybridisation for the S-phase marker PCNA identified discrete “islands” of CD24+/PCNA+ cells in Ptch1 deleted medulloblastoma, while adult wild type cerebella were predominantly PCNA-/CD24-." (PMID 30657775, 2019). "We identified elevated CD24 levels in all human medulloblastoma subgroups compared to normal cerebellum and normal brain tissue controls in 8 non-overlapping, independent gene expression-profiling studies (p<0.001)." (PMID 30657775, 2019). "Co-labelling with CD15 identified little CD24+/CD15+ co-expression in any of the four medulloblastoma subgroups." (PMID 30657775, 2019). "This study reports the use of CD24 and CD15 to isolate a GCP-like TIC population in Ptch1 deleted medulloblastoma, and suggests CD24 expression as a marker to help stratify human WNT tumours from other medulloblastoma subgroups." (PMID 30657775, 2019). "To this end we wanted to further characterise the expression of CD24 on Ptch1 deleted medulloblastoma." (PMID 30657775, 2019). "In Ptch1lox/lox;GFAPcre medulloblastoma high CD24 expression was observed throughout the tumour mass." (PMID 30657775, 2019). "Using a fluorescence-activated cell sorted (FACS) CD antibody panel, we identified CD24 as a marker of TICs in Ptch1 deleted medulloblastoma." (PMID 30657775, 2019). "Notably, the immune checkpoints genes coding for CD24 and B7-H3 were highly expressed in medulloblastoma, suggesting that they can constitute more suitable targets for an immune-targeted approach." (PMID 36825029, 2023). "Regardless, the CD24 role in medulloblastoma should be further investigated as this may be a promising target for the blockade approach in this tumor." (PMID 36825029, 2023). "Co-labelling with CD15 and CD24 allowed for the identification of a more mitotic and tumorigenic CD15+/CD24+ cell population within Ptch1 deleted medulloblastoma, illustrating that the CD24 TIC population could be further purified with CD15." (PMID 30657775, 2019). "Having shown that the expression of CD24 is significant in our murine model we sought to ascertain its relevance in human medulloblastoma and its four subgroups: WNT, SHH, Group 3 and Group 4, whose stratification is based on tumour location and genetic inception." (PMID 30657775, 2019).
medulloblastoma (continued). "To determine whether CD24 labels TICs in medulloblastoma, we investigated the tumour propagating potential of CD24+ and CD24- Ptch1lox/lox;GFAPcre cell populations." (PMID 30657775, 2019). "CD24/CD15 co-expression identified a correlation with high CD15 expression and low CD24 expression on WNT subgroups of medulloblastoma, with high CD24 expression and low CD15 expression correlated with SHH, Group 3 and Group 4 classifications, suggesting CD24 as a marker of non-WNT medulloblastoma." (PMID 30657775, 2019). "In primary Ptch1lox/lox;GFAPcre medulloblastoma, CD24 expression showed 1.6-fold up-regulation (82.10+/-3.07%) compared to equivalent aged wild type cerebella (50.58+/-2.55%; p<0.001), and 3.15-fold up-regulation compared to P7 wild type GCPs (26.56+/-9.45%; p = 0.003)." (PMID 30657775, 2019). "In situ hybridisation analysis identified CD24 RNA expression throughout the white matter and molecular layer of WT cerebella and disseminated expression throughout the Ptch1lox/lox;GFAPcre medulloblastoma." (PMID 30657775, 2019). "In our screen, CD24+ cells were highly positive for the stem/progenitor marker Sox2, whose expression has been shown to label stem-like cells in the murine brain, and has been shown to be required for SHH-associated medulloblastoma formation." (PMID 30657775, 2019). "In addition, CD24 has been reported to be expressed on human medulloblastoma, but its expression on murine models of medulloblastoma has yet to be fully investigated." (PMID 30657775, 2019). "We next investigated whether co-labelling of CD15 and CD24 could further purify a TIC cell population in Ptch1 deleted medulloblastoma." (PMID 30657775, 2019). "Regarding CD24 levels, the SHH and Group 4 medulloblastomas showed higher expression levels and the WNT subgroup, and the non-tumor tissue presented significantly lower expression levels than the remaining subgroups." (PMID 36825029, 2023). "To investigate a possible correlation of CD133 expression with CD24 we looked at the expression of CD24 on CD133 sorted populations in Ptch1lox/lox;GFAPcre medulloblastoma." (PMID 30657775, 2019). "Ongoing work is required to elucidate the role and function of CD15, CD24 and CD133 in medulloblastoma with the hope of utilising these markers to successfully eliminate TICs." (PMID 30657775, 2019). "To this end we selected CD24, CD15 and CD133 to investigate as TIC markers in Ptch1lox/lox;GFAPcre medulloblastoma." (PMID 30657775, 2019). "Of the antibodies tested, CD15, CD24 and CD133 have previously been reported in human medulloblastoma." (PMID 30657775, 2019). "CD24 and CD15 expression has been reported to be up-regulated on human medulloblastoma but little is known about their expression and correlation with patient survival on a subgroup level." (PMID 30657775, 2019). "Significantly higher CD24 expression levels were observed in SHH (p<0.0001), Group 3 (p = 0.0049) and Group 4 (p<0.0001) medulloblastoma subgroups compared with WNT subgroups." (PMID 30657775, 2019). "Altogether, CD276 and CD24 are the most attractive immune checkpoints to be targeted in medulloblastoma, given their higher expression in tumors than in non-tumor tissue and their association with worse prognosis." (PMID 36825029, 2023). "We further observed in our cohort and in a large dataset of medulloblastomas and non-tumor brain tissue that CD24 expression is significantly higher in all molecular medulloblastoma subgroups except WNT, which showed similar expression levels." (PMID 36825029, 2023). "Importantly, the analysis revealed overexpression of CD24 and CD276, which can constitute prognostic biomarkers and attractive immunotherapy targets for medulloblastomas." (PMID 36825029, 2023). "CD15 and CD133 expression have been identified on TICs within murine Ptch1 deleted medulloblastoma, but until now CD24 expression had not been extensively investigated in any murine model of medulloblastoma." (PMID 30657775, 2019).
medulloblastoma (continued). "While CD24 expression has previously been shown to be elevated in human medulloblastoma there have been until now no studies examining the expression of CD24 between the subgroups." (PMID 30657775, 2019). "CD24 expression has previously been shown to label proliferating, progenitor-like cells of the cerebellum so we hypothesised that CD24 would label TIC’s in Ptch1lox/lox;GFAPcre medulloblastoma." (PMID 30657775, 2019). "Together these results indicate that CD24 expression is elevated on non-WNT subgroups of human medulloblastoma and may serve as a selective marker in the treatment of Group 3, Group 4 and SHH medulloblastoma subgroups." (PMID 30657775, 2019). "CD24 alone could not isolate putative stem cells, but may label cells transitioning from a Sox2 fate to a neural progenitor or radial glial cell fate, cell types frequently observed within medulloblastoma." (PMID 30657775, 2019). "In this study no distinct expression profiles were observed with CD133 and CD24 co-staining, indicating that CD24 expression was not correlative with CD133 expression when identifying stem-like cells in Ptch1 deleted medulloblastoma." (PMID 30657775, 2019). "Co-staining with the Purkinje neuron marker Calbindin identified co-labelling with CD24 throughout the Purkinje layer of WT cerebella, but not with CD24+ cells in the IGL of Ptch1lox/lox;GFAPcre medulloblastoma." (PMID 30657775, 2019). "Moreover, it confirmed the overexpression of CD24 and CD276 in medulloblastomas compared with the non-tumor tissue." (PMID 36825029, 2023).
metastatic melanoma (3 papers, 2008 to 2025). A melanoma that has spread from its primary site to another anatomic site. "Using B16-F10 as the cancer cell model, we explored the tumorigenic properties of apoptotic and granular CD24+veFSClow cells, which are actively shed in the exponentially growing metastatic melanoma cell lines." (PMID 39136818, 2025). "Taken together, our findings suggest that seemingly apoptotic metastatic melanoma cell lines express CD24 and possess tumorigenic properties in vitro." (PMID 39136818, 2025).
oral cancer (3 papers, 2021 to 2023). "Perhaps the variable cell-type specific effect underlies the paradoxical role of CD24 in oral cancer." (PMID 34712602, 2021). "Thus, we logically elucidated the molecular mechanism underlying CD24 mediated β-catenin degradation via AKT in oral cancer cells." (PMID 34712602, 2021). "Immunohistochemical staining was used to examine the protein levels of IFIT2 and CD24 in oral cancer patients." (PMID 36979874, 2023). "The role of miR-146a/CD24/AKT/β-catenin axis in maintaining the oral cancer stem cell populations is thus mechanistically evident." (PMID 34712602, 2021). "Our study thus provides strong evidence which suggest that miR-146a promotes CSC characteristics of oral cancer cells by down-regulating CD24." (PMID 34712602, 2021). "This justifies the involvement of miR-146a in negative regulation of CD24 expression in oral cancer stem cells." (PMID 34712602, 2021). "In the present study, we provide evidence that miR-146a mediated downregulation of CD24 confers CSC phenotype in oral cancers." (PMID 34712602, 2021). "We propose that miR-146a/CD24/AKT/β-catenin axis influences the stemness characteristics of oral cancer cells." (PMID 34712602, 2021). "(F) Detection of EpCAM+Vim+CD24+ cells in the stroma surrounding an oral cancer tumour specimen." (PMID 37975646, 2023). "We have previously identified both EpCAM and CD24 as CSC markers that, alongside the mesenchymal marker Vimentin, identify EMT CSCs in human oral cancer cell lines." (PMID 37975646, 2023).
osteoporosis (3 papers, 2022 to 2025). A condition of reduced bone mass, with decreased cortical thickness and a decrease in the number and size of the trabeculae of cancellous bone (but normal chemical composition), resulting in increased fracture incidence. "Specifically, the odds ratio (OR) of IgD+ CD24+ %B cell (B cell panel) risk on Osteoporosis was estimated to be 0.9986 (95% CI = 0.9978~0.9996, P<0.01)." (PMID 39086903, 2024). "The OR of CD24+ CD27+ %B cell (B cell panel) risk on Osteoporosis was estimated to be 0.9991 (95% CI = 0.9984~0.9998, P = 0.021)." (PMID 39086903, 2024). "Consequently, MR analyses suggest that a higher proportion of B cell subgroups expressing IgD and CD24 correlates with a reduced risk of osteoporosis." (PMID 39086903, 2024). "For example, increased CD45RA expression on CD39+ resting Treg, increased expression of CD25 on resting Treg, and higher level of CD24 on memory B cell may be implicated in predisposition to osteoporosis." (PMID 36341399, 2022). "IgD+CD24+B cells are associated with osteoporosis and may reduce its risk." (PMID 40909263, 2025). "CD24, CD27, CD25 from B cells are protective factors against osteoporosis, and similar findings have been discussed, but more in-depth mechanisms of action remain to be investigated." (PMID 39086903, 2024). "According to MR results, the traits IgD+ CD24+ %B cells, CD24+ CD27+ %B cells, and CD25 on IgD+ (B cell panel) have been identified as protective factors against osteoporosis." (PMID 39086903, 2024).